INS (insulin)
Diseases named in the same sentence as INS in open-access papers (continued):
Sharing a sentence is not in itself a finding about the gene and the disease.
type 2 diabetes (continued). "Most of the type 2 susceptibility genes identified by GWAS in Western population play a role in insulin secretion which correlates well with the type 2 diabetes phenotype in that population." (PMID 20625434, 2010). "When insulin secretion is waning in Nile rats, fasting glucose remains elevated, even as it does with fasting in advanced type 2 diabetes in humans." (PMID 20398338, 2010). "Recently, resveratrol has received increasing attention for the prevention of type 2 diabetes because it not only improved insulin sensitivity of mice fed a high−fat diet but also increased insulin secretion in pancreatic β−cells." (PMID 23554653, 2010). "Although the physiology of human and mouse are clearly distinct, they nonetheless share many common derangements in insulin action and beta cell function that lead to type 2 diabetes." (PMID 20624298, 2010). "In individuals with type 2 diabetes, the increasing insulin requirements, owing to insulin resistance or excess β-cell stimulation by sulfonylurea, result in β-cell overload with impaired processing of IP into insulin and C-peptide." (PMID 20415692, 2010). "In vivo, the decrease in circulating TNF-α level has been reported to be involved in improvement of β-cell function of type 2 diabetic patients receiving transient intensive insulin therapy." (PMID 21113299, 2010). "In type 2 diabetes patients, use of oral hypoglycaemic agents for those inadequately controlled on dietary therapy was 38% and use of insulin for those inadequately controlled on oral hypoglycaemics was 39%." (PMID 20553622, 2010). "Type 2 diabetes is a complex metabolic disorder characterized by impaired insulin secretion and action." (PMID 20187968, 2010). "Type 2 diabetes can be controlled with diet and exercise, and with drugs that help the pancreas make more insulin or that make cells more sensitive to insulin." (PMID 20421924, 2010). "Despite these developments, insulin-naïve patients with type 2 diabetes are still reluctant to initiate insulin therapy." (PMID 20370840, 2010). "The Insulin signalling and Type II diabetes pathways, which are deeply associated with glucose metabolism, were differentially expressed in both groups." (PMID 20540717, 2010). "Glitazones bind to PPAR, specifically PPARγ, and activate the receptor, which in turn increases the insulin sensitivity and are clinically used to control hyperglycemia in type 2 diabetes." (PMID 20613990, 2010). "Similar results have been obtained with insulin detemir when added as basal insulin for type 2 diabetic patients insufficiently controlled with OADs." (PMID 20589066, 2010). "To elucidate further the relationship between HIV-R female sex workers with the diabetic or prediabetic phenotype, we investigated the expression patterns of genes in the insulin signaling pathway which are significantly perturbed during Type 2 diabetes state." (PMID 21108831, 2010). "Research Question 2: How do the item frequency distributions of expectations differ from experiences in individuals with type 2 diabetes who are insulin-naïve and who subsequently experience an inhaled insulin?" (PMID 20370840, 2010). "Patients with type 2 diabetes treated with insulin experienced the greatest increases in body weight (+4.0 kg [p < 0.0001]), followed by chlorpropamide (+2.6 kg [p < 0.001]), and glibenclamide (+1.7 kg [p < 0.001]) when compared with conventional therapy." (PMID 20804556, 2010). "In the treating to target in type 2 diabetes (4T) trial detemir was also less effective than premix at controlling HbA1c after 1 year of treatment, but with lower insulin doses and with less weight gain." (PMID 20946269, 2010). "Second, we only analyzed the effects of these loci on insulin sensitivity and secretion in the normal glucose regulation subjects as most of the type 2 diabetes patients were receiving glucose lowering therapy." (PMID 21103350, 2010).
type 2 diabetes (continued). "Thiazolidinediones (TZDs) activate peroxisome proliferator-activated receptor gamma (PPARγ) and are used clinically to help restore peripheral insulin sensitivity in Type 2 diabetes (T2DM)." (PMID 20454453, 2010). "Insulin is normally added to oral glucose-lowering drugs in people with type 2 diabetes when glycaemic control becomes suboptimal." (PMID 20946269, 2010). "The onset of frank type 2 diabetes is characterised by a progressive decline in insulin sensitivity together with progressive deterioration in beta-cell function leading to reduced insulin secretion." (PMID 20860758, 2010). "Based on the gene array, we found that skin γδ T cells differentially express NR4A1 and NR4A3, two orphan nuclear receptors which have been shown to sensitize muscle to insulin and have been reported to be underexpressed in obesity and type 2 diabetes." (PMID 20625397, 2010). "High doses of anti-inflammatory drugs, such as aspirin and salicylates, improve glucose metabolism in insulin resistant and type 2 diabetic patients." (PMID 20948968, 2010). "Once OADs are unable to maintain glycaemic control, insulin treatment in type 2 diabetes is often initiated by basal insulin supplementation in the evening, while maintaining OADs during the day." (PMID 20415692, 2010). "Two different motives have been identified for type 2 diabetes in ax_SafetyDB: insufficient insulin production and insulin resistance." (PMID 21143928, 2010). "It has been reported in newly diagnosed type 1 diabetes, in poorly controlled type 2 diabetes following the initiation of insulin therapy, and in underweight patients on large doses of insulin." (PMID 21274337, 2010). "Data suggest impairment in the ability of insulin to suppress hepatic production of large TG-rich VLDL (VLDL-TGs) in patients with type 2 diabetes results in a subsequent elevation in plasma TG levels." (PMID 21172030, 2010). "This indicates that treatment of type 2 diabetes becomes more costly with disease progression because insulin is increasingly prescribed with progression." (PMID 20854689, 2010). "Thiazolidinediones (rosiglitazone and pioglitazone) improve insulin sensitivity by acting via the peroxisome proliferator-activated receptors and are used as blood glucose lowering agents in Type 2 diabetes." (PMID 21532773, 2010). "In a previous randomized, controlled trial, using an earlier version of the IITQ (the ITQ), insulin naïve individuals with type 2 diabetes were randomized to active TI or placebo TI therapy at mealtimes." (PMID 20334647, 2010). "We selected a number of genes from the insulin signaling pathway and some that had previously been shown to be related with type 2 diabetes)." (PMID 21108831, 2010). "On 20q13 lies DOK5 that seems to be a strong functional and positional candidate for type 2 diabetes and obesity because of its involvement in insulin signaling and immune responses." (PMID 20187968, 2010). "Insulin detemir therapy also provided more predictable glycaemic control and less intra-patient variability than NPH insulin in both type 1 and type 2 diabetes." (PMID 20618882, 2010). "Discreteness of insulin delivery system has been shown to be rated as an important attribute of such systems by patients with type 2 diabetes and has been suggested as a driver of insulin delivery system satisfaction and/or preference." (PMID 20370840, 2010). "The results of this study provide evidence that the IITQ is a reliable instrument for assessing a broad range of patient reported outcomes (PRO) in patients with type 1 or type 2 diabetes using inhaled insulin." (PMID 20334647, 2010). "The effects of native banana starch (NBS) and soy milk (control) on body weight and insulin sensitivity in obese type 2 diabetics were compared using a blind within-subject crossover design." (PMID 20623003, 2010).
type 2 diabetes (continued). "Type 2 diabetes (T2D) is a metabolic disorder characterized by impaired insulin-stimulated glucose uptake in muscle and fat, altered glucose-induced insulin secretion, and increased hepatic glucose production." (PMID 20470430, 2010). "A recent study by Derosa and colleagues (2010) compared the effects of exenatide versus glibenclamide on glycemic control, body weight, beta-cell function, insulin resistance, and inflammatory state in 128 patients with type 2 diabetes." (PMID 20804556, 2010). "After participation in this program, the pilot group reported a statistically significant increase in confidence in their ability to select, initiate, and adjust insulin for patients with type 2 diabetes." (PMID 20097652, 2010). "The mechanism by which the type 2 diabetes loci influence birth weight is presumably by influencing fetal insulin availability." (PMID 21152014, 2010). "In a post hoc analysis of 2 studies in patients with type 2 diabetes, pramlintide (n = 254) or placebo (n = 244) was added to insulin therapy." (PMID 20804556, 2010). "This implies an average time to initiation of insulin of at least 11.5 years from initial diagnosis of type 2 diabetes." (PMID 19804622, 2009). "Type 1 (T1DM) and type 2 diabetes (T2DM) both result from the metabolic consequences of insufficient insulin effect, and have similar complications but appear to be due to completely distinct pathogenetic mechanisms." (PMID 19691832, 2009). "In clinical trials in patients with type 1 or type 2 diabetes, glargine was shown to be as effective as NPH insulin in lowering HbA1c levels and was also associated with significantly fewer episodes of symptomatic and nocturnal hypoglycaemia." (PMID 19152692, 2009). "Weight gain is a potential barrier to insulin therapy in patients with type 2 diabetes; patients need to have realistic expectations and manage potential weight gain with a regimen of healthy diet and exercise." (PMID 19780866, 2009). "Impaired glucose tolerance precedes type 2 diabetes and, by the time of clinical diagnosis, patients have lost about half of their β-cell insulin-producing capacity." (PMID 19780866, 2009). "It is striking that the most significantly upregulated pathway in the first degree relatives is Insulin Signaling, whereas it is the single most downregulated pathway in people with type 2 diabetes." (PMID 19668377, 2009). "PPARγ activation in type 2 diabetic patients results in a marked improvement in insulin and glucose parameters, resulting from an improvement of whole-body insulin sensitivity." (PMID 20182551, 2009). "Because PPARγ activation by thiazolidinedione increased insulin sensitivity in type 2 diabetes, understanding the long term impact of PPARγ activation on steroid sex hormones in males is critical." (PMID 19536350, 2009). "Insulin signaling was significantly upregulated in first degree relatives, and significantly downregulated in type 2 diabetes patients." (PMID 19668377, 2009). "A key feature of type 2 diabetes is that pancreatic β-cells fail to release sufficient amounts of insulin despite elevated blood glucose levels." (PMID 19344500, 2009). "This compensation is lost in people with type 2 diabetes where expression of insulin signaling molecules is reduced." (PMID 19668377, 2009). "Downregulation of Glut4 in adipose tissue is a typical feature of insulin-resistant states, such as obesity and type 2 diabetes." (PMID 19460132, 2009). "The authors concluded that it was worthwhile continuing an insulin sensitiser in type 2 diabetes patients switched to insulin." (PMID 19568428, 2009). "A recent consensus statement from the UK recommended premix analogues BID (intensifying to TID as required) as a treatment option for patients with type 2 diabetes switching from basal insulin." (PMID 19780866, 2009). "In most studies, traits quantified in the type 2 diabetes models include glucose level, insulin level, body weight, gland mass, lipid level or body fat amount." (PMID 19575795, 2009).
type 2 diabetes (continued). "Treatment regimens comprising premixed insulin are an established treatment option when starting insulin in type 2 diabetes patients." (PMID 19210701, 2009). "currently, pparγ ligands are used in clinics for their anti-inflammatory and insulin-sensitizing effects in diseases such as psoriasis, atherosclerosis, inflammatory bowel disease and type 2 diabetes." (PMID 19680557, 2009). "While insulin therapy is required from the onset of diagnosis in type 1 disease, its role in type 2 diabetes requires consideration as to when to initiate and advance therapy." (PMID 19573240, 2009). "Overall, 39% of patients with type 1 diabetes and 21% with type 2 diabetes had received bolus insulin doses in the previous 12 months prior to the switch, whilst 0% and 38% of patients with type 1 and type 2 diabetes respectively were taking an OAD." (PMID 19220880, 2009). "Prior to the DreamTel program, for the initiation of insulin in community members with type 2 diabetes, it was standard practice for primary care providers to arrange for admission to hospital for insulin initiation." (PMID 19426530, 2009). "Epidemiological studies show that 7% of PD patients have type 2 diabetes or suffer from insulin desensitization." (PMID 27713238, 2009). "Our results show for the first time that insulin signaling is significantly downregulated in people with type 2 diabetes, whereas it is significantly upregulated in first degree relatives." (PMID 19668377, 2009). "Recent data have shown that type 2 diabetes patients in the UK delay initiating insulin on average for over 11 years after first being prescribed an oral medication." (PMID 19804622, 2009). "International data from routine clinical practice show that glycaemic control in patients with type 2 diabetes is poor on average, even in patients using insulin: almost 50% of patients in the IMPROVE observational study had HbA1c≥ 9.0% at the baseline visit." (PMID 19780866, 2009). "Here, 191 patients with type 2 diabetes, previously insulin-naïve, were randomised 2 : 1 to BIAsp 30 OD or to an optimised OAD regimen." (PMID 19780866, 2009). "Differences in insulin signaling-related effects are likely to underlie the differences between DPN in insulin-deficient type 1 and hyperinsulinemic type 2 diabetes." (PMID 19834568, 2009). "The study performed in insulin resistant patients with type 2 diabetes demonstrated a diminished stimulation of muscle mitochondrial ATP production by insulin." (PMID 19333447, 2009). "Insulin signaling defects observed in muscle from people with type 2 diabetes has previously been reported to be specific for the metabolism regulating part of the pathway, thereby leaving the MAP kinase part of the pathway intact." (PMID 19668377, 2009). "When added to insulin regimens, pioglitazone confers a small advantage in terms of HbA1c in type 2 diabetes patients with previous inadequate glucose control, but at the cost of increased hypoglycaemia and weight gain." (PMID 19568428, 2009). "Improving treatment and disease management in type 2 diabetes is therefore crucial if long-term vascular complications are to be minimised, and intensification of failing insulin therapy is a key step in this process." (PMID 19780866, 2009). "Circulating levels of RBP4 are elevated in subjects with obesity and type 2 diabetes and lower with improved insulin sensitivity." (PMID 19589139, 2009). "Initiating insulin therapy with BIAsp 30 OD is also a successful strategy for improving glycaemic control in patients with type 2 diabetes failing on oral therapy." (PMID 19780866, 2009). "This compares favourably with data from a RCT, in which 33% of patients with type 2 diabetes achieved this target using bid BIAsp 30 (approximately one-third of patients were previously treated with basal insulin) after 26 weeks of therapy." (PMID 19504715, 2009).
type 2 diabetes (continued). "In ZDF fa/fa rats, a genetic model of type 2 diabetes with decreased functional β-cell mass, insulin release of βhigh-cells from ZDF fa/fa rats was strongly diminished compared to βhigh-cells from control ZDF lean rats." (PMID 19440374, 2009). "Accordingly, TZD-induced decreases in NEFA correlate with improvements in both muscle and hepatic insulin sensitivity in patients with type 2 diabetes." (PMID 20182551, 2009). "Type 1 diabetes results from the destruction of beta cells within the islets in the pancreas, whereas type 2 diabetes results from initial insulin resistance." (PMID 19208189, 2009). "In October 2008, an international expert panel met to review the current guidelines for insulin intensification with BIAsp 30 in patients with type 2 diabetes, with the aim of developing practical guidance for general and specialist practitioners." (PMID 19780866, 2009). "Pancreatic islets are thought to play a key role in the pathophysiology of Type 1 and Type 2 diabetes through the failure of islet beta cells to secrete sufficient quantities of insulin to regulate blood glucose." (PMID 19957062, 2009). "In summary, this study for the first time shows a striking difference in the gene expression of insulin signaling molecules between people with type 2 diabetes and first degree relatives in skeletal muscle." (PMID 19668377, 2009). "Insulin is crucial to regulating blood glucose, and reduced insulin secretion is a key feature of both Type 1 and Type 2 diabetes." (PMID 19957062, 2009). "For patients with type 2 diabetes, insulin therapy is indicated after failure to achieve glycaemic control despite increasingly aggressive treatment with oral antidiabetic drugs (OADs) that are prescribed in combination with lifestyle changes." (PMID 19220880, 2009). "ZO rats were insulin-resistant at 7 and 14 weeks, with normal glucose but raised insulin levels, and developed mild type 2 diabetes at 21 weeks." (PMID 20030821, 2009). "Risk factors for type 2 diabetes, viz, plasma insulin and glucose, beta-cell function (measured as HOMA B%), and insulin sensitivity (measured as HOMA S%) remained stable over the first 12 weeks of diet and activity intervention." (PMID 20169118, 2009). "In order to elucidate its role, we determine the levels of PTHrP, insulin and c-peptide in type 2 diabetics and in normal subjects in the fasting state." (PMID 19727413, 2009). "Given the progressive nature of the disease, most patients with type 2 diabetes inevitably proceed from oral agent monotherapy to combination therapy and, ultimately require exogenous insulin replacement." (PMID 19607676, 2009). "P. obesus fed with a HE diet displayed a characteristic heterogeneity in their blood glucose and insulin levels with a subset group displaying type 2 diabetes symptoms." (PMID 19822001, 2009). "We included eight trials that examined the benefits of adding pioglitazone to an insulin regimen and studied a total of 3092 patients with type 2 diabetes." (PMID 19568428, 2009). "When added to insulin regimens, pioglitazone confers a small but clinically useful decrease in HbA1c of 0.58% in type 2 diabetes patients with previous inadequate glucose control." (PMID 19568428, 2009). "We show for the first time that genes involved in insulin signaling are significantly upregulated in first degree relatives and significantly downregulated in people with type 2 diabetes." (PMID 19668377, 2009). "Multiple clinical studies have investigated the effects of TZDs on glucose disposal rates and the insulin signal transduction system in type 2 diabetic patients." (PMID 20182551, 2009). "As an attempt to investigate the role of PTHrP in diabetes, we performed serum determinations of PTHrP, insulin, and c-peptide in type 2 diabetics and in normal subjects in the fasting state." (PMID 19727413, 2009).